MYCL (MYCL proto-oncogene, bHLH transcription factor)
Diseases named in the same sentence as MYCL in open-access papers (continued):
Sharing a sentence is not in itself a finding about the gene and the disease.
cancer (continued). "The MYC proto-oncogenes (MYC, MYCN, MYCL) have been extensively studied since their discovery in the early 1980’s and they continue to be of great interest as the most commonly deregulated genes in human cancer." (PMID 29799508, 2018). "Some studies have suggested that the S allele of the MYCL oncogene, which results from an intragenic EcoRI restriction fragment length polymorphism (RFLP), may be associated with cancer susceptibility." (PMID 8980399, 1996). "In addition, these results may help to explain why the oncogenic activity of MCPyV ST is limited to MCC because of its dependency on MYCL or if this virus is capable of inducing MYCL and cancers in other tissue types." (PMID 29028833, 2017). "Among them, MYC is the most widely expressed, covering almost all cancers, whereas MYCN and MYCL are expressed mainly in neuroblastoma and small cell lung cancer, respectively." (PMID 40732268, 2025). "Screening 107 overall survival-related cancer genes and 402 interacting gene pairs, 6 genes: CRLF2, HSP90AA1, MAP2K1, PAFAH1B2, MYCL and SET genes, were identified and a transcriptional score was obtained." (PMID 37897503, 2023). "MYCL is a member of the MYC proto-oncogene family and regulates cellular programs orchestrating multiple hallmarks of cancer, including proliferation, metabolism, invasiveness, and immune surveillance." (PMID 37897503, 2023). "To explore the relationship between MYCL and HLA-I in MCPyV– MCC and other cancers, we first evaluated the genomic status of MYCL in MCPyV– MCC." (PMID 35775490, 2022). "MYCL1, (MYCL proto-oncogene, BHLH transcription factor), and TOP1 (DNA topoisomerase 1) have been suggested to play a role in various types of cancer." (PMID 35659227, 2022). "In fact, at least 28% of human cancers have amplified or translocated MYC, MYCN, or MYCL; in many more, MYC is upregulated downstream of other oncogenic insults." (PMID 34299381, 2021). "The MYC family of transcription factors, including c-MYC (MYC), MYCL and MYCN are amongst the most commonly altered genes in cancer, including paediatric cancers." (PMID 34195095, 2021). "Moreover, focal CNA amplifications encompassed genomic peaks that harbored canonical cancer genes including those found at HPV-integrated hotspots (MYC, MYCN, MYCL, SOX2, NR4A2, and ANKRD12), and others (CCNE1, SMAD2, BCL2L1, and GNAS)." (PMID 36216793, 2022). "In this regard, we have seen that MYCL is also highly expressed in PC localized tumours (Pan-Cancer database) (data not shown)." (PMID 33635497, 2021). "In SCLC, previous studies indicated that JQ1 targeted MYCL and ASCL1 to inhibit cancer cell growth." (PMID 29156797, 2017). "However, they shared with carcinomas a similar prevalence of copy gains in several genes, including the chromosome 5p genes TERT, SDHA, and RICTOR, but also SRC and MYCL." (PMID 27873319, 2017).
tumor (63 papers, 1989 to 2025). "The association of MYCN and MYCL in this tumor is a striking and unique observation, although isolated MYCL amplifications have been sporadically observed in SHH tumors and MYCN is one of the most frequently amplified genes in SHH tumors." (PMID 26857864, 2016). "Theoretically, ST could also function as a tumor initiator through its association with MYCL and the chromatin remodeling complex EP400, which leads to increased transcription of several pro-oncogenic genes." (PMID 33435392, 2021). "Biologically, ASCL1 plays a crucial role in tumor initiation and maintenance by regulating MYCL, SOX2, RET, BCL2, and DLL3, all of which contribute to NE differentiation and tumor survival." (PMID 40333678, 2025). "Targeted overexpression of MYCL in a mouse lung cancer model markedly accelerated tumor development." (PMID 30060526, 2018). "Thus, the association between the TI-signature and MYC/MYCL/MYCN amplification status were examined and the results indicated that the TI-signature score represented the MYC pathway in the tumor cells." (PMID 34122516, 2021). "For instance, CRISPR‐mediated depletion of MYCL or MYCN in mouse tumor‐derived SCLC could reduce tumor formation capacity, but MYC could not." (PMID 32281704, 2020). "The tumor promoting MYC, which is besides MYCN Proto-Oncogene, BHLH Transcription Factor (MYCN) and MYCL Proto-Oncogene, BHLH Transcription Factor (MYCL) part of the MYC transcription factor (TF) family, also impacts proliferation and malignant transformation." (PMID 38896334, 2024). "According to The Cancer Genome Atlas (TCGA), MYC amplification occurs in 21% of all tumor samples, whereas that of the MYCN and MYCL paralogs are much less frequent." (PMID 34503295, 2021). "Although differential expressions have been described in different tumour types, the MYC family proteins (MYC, MYCN and MYCL) have highly conserved domains, which suggests that the mechanisms through which they carry out tumorigenesis are similar." (PMID 33635497, 2021). "The authors showed that MYCL cooperates with the tumor derived MCPyV early region (expressing sT and tLT) to induce expression of MCT1 and knockdown of the p65 subunit of NFκB reduced sT, as well as sT+MYCL stimulated MCT1 expression." (PMID 32635198, 2020). "Among the 10 amplification-based oncogenes, we identified that six genes (MDM2, MYC, MYCL, MYCN, NKX2-1, and SKP2) were amplified and overexpressed in ≥10 tumor samples." (PMID 28377632, 2017). "Among the 10 amplification-based oncogenes, expression levels of MYC family genes, including MYC, MYCL, and MYCN, varied among tumor tissue samples." (PMID 28377632, 2017). "In our metastatic dataset along with additional primary SCLC patient tumor, circulating tumor cell‐derived xenograft, and patient‐derived xenograft (PDX) datasets, samples overexpressing MYC paralogs (MYC, MYCL, or MYCN) consistently displayed significantly lower CDKN1A expression." (PMID 37491889, 2023). "Interestingly, SCLC produces the only form of tumor in which all the MYC family genes (MYC, MYCN and MYCL) are found to be altered." (PMID 36765949, 2023). "Furthermore, treatment of iBAP-II represses neuroendocrine lineage-specific ASCL1/MYCL/E2F signaling in SCLC cell lines, and dramatically inhibits SCLC cell viability and tumor growth in vivo." (PMID 35194152, 2022). "Since there is no MYCL gene expression reported data on primary tumour or CTCs from PC patients we explored the public available databases in order to study MYCL status." (PMID 33635497, 2021). "However, the spheroid DNA of the same tumor was diagnosed as MSI-H in seven-marker on-chip analysis because it had multiple peaks shifted from the normal cell DNA for D2S123, BAT40 and MYCL." (PMID 30680068, 2018).
tumor (continued). "Furthermore, at the smaller-genomic scale level, ALK fusion-positive tumours were less amplified at the loci containing EGFR family genes, 7p11.2 (EGFR), 17q12 (ERBB2) and other loci, 1p34.3 (MYCL), 7p21.1, 8q24.21 (MYC), 16p13.3 and 17q25.1." (PMID 23289484, 2013). "To determine if MYC family proteins could cooperate with MCPyV IMR90 cells, we treated cells stably expressing ST, GFP, or p53DD + hTERT (PH) and MCPyV tumor-derived early-region (PHE) with inducible expression of MYC, MYCN or MYCL with dox for 48 hours and immunoblotted for HK2, MCT1 and LDHA." (PMID 27880818, 2016). "One tumor (case 5) showed MYCN and MYCL amplifications, and a 9q deletion encompassing PTCH1; no chromothripsis was seen in that tumor." (PMID 26857864, 2016). "While MYC is ubiquitously and highly expressed in cells throughout development and in adult tissues, MYCL expression is predominantly restricted to both neonatal and adult lung tissue; in contrast MYCN expression is tumor specific and is not usually expressed in human adult tissues." (PMID 36765949, 2023). "Tumor types, such as stomach adenocarcinoma, lung adenocarcinoma, breast invasive carcinoma, and hepatocellular carcinoma, also exhibit frequent MYC amplification, but not that of MYCN and MYCL gene paralogs." (PMID 34503295, 2021). "This putative negative correlation between the expression of MYC/MYCL/MYCN and HIF2A is supported by data retrieved from the databank of a published expression analysis of 81 SCLC tumor specimens showing that tumors with high pan-MYC expression generally express low levels of HIF2A (PMID: 26168399)." (PMID 28430666, 2017).
infection (7 papers, 2014 to 2025). The state of being infected such as from the introduction of a foreign agent such as serum, vaccine, antigenic substance or organism.
adenocarcinoma (1 paper, 2026). A common cancer characterized by the presence of malignant glandular cells. "MYCL expression strongly correlates with the neuroendocrine lineage regulators ASCL1 and INSM1 and inversely with adenocarcinoma-associated genes." (PMID 42001796, 2026).
MYCL also shares sentences with these, for which no sentence is quoted: breast carcinoma (5 papers); lymphoma (5); neuroendocrine carcinoma (5); Burkitt lymphoma (3); glioma (3); bladder cancer (2); colorectal cancer (2); endometrial carcinoma (2); Hepatic fibrosis (2); melanoma (2); oral cancer (2); Sepsis (2); squamous cell carcinoma (2); Alpha-thalassemia (1); ameloblastic carcinoma (1); ameloblastoma (1); astrocytoma (1); B-cell lymphomas (1); brain tumors (1); cardiovascular disease (1); colon cancer (1); ependymoma (1); glioblastoma (1); Hearing Loss (1); hematological cancer (1); Hodgkin's disease (1); Impaired glucose tolerance (1); Insulin resistance (1); kidney infection (1); large cell neuroendocrine carcinoma (1).
A further 18 diseases each share a sentence with MYCL in 1 paper.